SOX9 (SRY-box transcription factor 9)
Diseases named in the same sentence as SOX9 in open-access papers (continued):
Sharing a sentence is not in itself a finding about the gene and the disease.
pancreatic cancer (continued). "The acquired results demonstrate that the SOX9 protein exerts its multiple functions as a pleiotropic regulator of differentiation and a potential promoter of tumor growth in a cell-specific manner in pancreatic cancer cells." (PMID 35884771, 2022). "We tested whether high levels of SOX9 were sufficient to promote EMT in pancreatic cancer cells, which are classified as the tumor cell types with high SOX9 expression." (PMID 35205666, 2022). "It is hypothesized that the increased expression of SOX9 is necessary for the formation and maintenance of tumor phenotypes in pancreatic cancer cells." (PMID 35884771, 2022). "In this study we wanted to address whether SOX9 promotes EMT along with other metastatic traits in pancreatic cancer." (PMID 35205666, 2022). "It is hypothesized that the increased expression of SOX9 is necessary for the formation and maintenance of the tumor phenotype in pancreatic cancer cells." (PMID 35884771, 2022). "Thus, our results demonstrate the possibility of viewing SOX9 as a potential target for antitumor therapy for pancreatic cancer." (PMID 35884771, 2022). "In addition, we characterized the clinical relevance of SOX9 in pancreatic cancer using human biopsies." (PMID 35205666, 2022). "Moreover, the analysis of the available information from The Cancer Genome Atlas (TCGA) project associated high SOX9 expression with reduced overall survival (p = 0.011), showing the relevance of SOX9 in the clinical progression of pancreatic cancer." (PMID 35205666, 2022). "Third, the therapeutic targeting of the activity and expression of the SOX9 protein, despite its multiple effects on intracellular activities, may slow down proliferation and induce apoptosis in pancreatic cancer cells." (PMID 35884771, 2022). "It has been shown that SOX9 is significantly overexpressed in high-grade pancreatic tumors and in chemotherapy-treated patients, compared to chemo-naive patients, and reduction in its expression is significant for the decrease in tumor growth and successes of combined chemotherapeutic regiments." (PMID 35408514, 2022). "Therefore, taking into account the significant intratumoral and intertumoral heterogeneity of PDAC, we conducted a relative assessment of changes that occur after the downregulation of SOX9 expression via siRNA in different pancreatic cancer cell lines." (PMID 35884771, 2022). "The presence of the extended expression downregulation by siSOX9 allowed us to investigate how the downregulation of SOX9 may affect the mobility and migratory potential of pancreatic cancer cells after their xenotransplantation into Danio rerio embryos." (PMID 35884771, 2022). "Grimont revealed that SOX9 could regulate the ERBB signaling pathway in the development of pancreatic cancer." (PMID 34320917, 2021). "In acinar cell plasticity and pancreatic cancer initiation, NFATc4 was found to be overexpressed and localized in the nucleus, thus activating the inflammation-induced epidermal growth factor receptor signaling pathway and upregulating the expression of Sox9." (PMID 33511023, 2021). "We hypothesized that MECOM plays a role during acinar cell dedifferentiation, an event that initiates pancreatic tumor development, and this in connection to SOX9 and ERK signaling." (PMID 33762742, 2021). "Interestingly, SOX9 is a known regulator of acinar cell dedifferentiation and a driver of pancreatic tumor formation." (PMID 33762742, 2021). "Moreover, epigenetic regulation of Sox9 expression by DNA methylation was observed in pancreatic cancer." (PMID 27105493, 2016). "Thus, we may conclude that SOX9 knockdown affects expression of genes related to immunity in pancreatic cancer cells and that the biological sense of such influence should be additionally studied." (PMID 40141294, 2025).
pancreatic cancer (continued). "The necessity of SOX9 for transcriptional plasticity has previously been seen in breast, lung, and pancreatic cancers; however, it has been unclear whether SOX9 is merely a marker of plasticity or if it can induce these stem properties in non-CSCs to survive cytotoxic chemotherapy." (PMID 41031891, 2025). "In addition, activation of the NF-kB pathway in pancreatic cancer stem cells is dependent on methylation of the downstream regulatory gene SOX9, and DNA methyltransferase inhibitors may represent a novel therapeutic option for pancreatic cancer treatment." (PMID 36672697, 2023). "Therefore, the downregulation of SOX9 expression levels in the investigated pancreatic cancer cell lines induced specific and multidirectional changes in the expression of the markers and regulators of mesenchymal and epithelial differentiation in a cell-specific manner." (PMID 35884771, 2022). "Thus, confirming previous results revealing that SOX9 inhibition reduces tumor growth, immunohistochemistry analysis showed lower staining of SOX9 as well as reduction in Ki67 positive cells in gastric and pancreatic tumors with reduced SOX9." (PMID 31941916, 2020). "In pancreatic cancer, the oncogene KRAS induces the expression of SOX9 at both the mRNA and protein levels, including its phosphorylated form, thereby promoting SOX9 nuclear translocation and transcriptional activity." (PMID 41268614, 2026). "In order to study the role of SOX9 in pancreatic cancer further, we have conducted full-transcriptome analysis of cells from two PAAD cell lines, PANC-1 and COLO357, under conditions of suppression of SOX9 gene expression using siRNAs." (PMID 40141294, 2025). "Treatment of pancreatic tumor organoids with recombinant NTN1 enhanced cell growth, epithelial-mesenchymal transition (EMT), and cancer stemness with the upregulation of ZEB1 and SOX9 through NEO1-mediated activation of focal adhesion kinase (FAK)." (PMID 40777309, 2025). "To investigate the function and importance of SOX9 for tumor prognosis and therapy further, we performed a full transcriptome analysis of PANC-1 and COLO357 pancreatic cancer cells with SOX9 activity suppressed by RNA interference." (PMID 40141294, 2025). "In this work, we demonstrate that SOX9 is necessary and sufficient for the activation and modulation of a tumorigenic EMT in pancreatic cancer, in a process that requires the activation of stemness pathways, but not critical EMT factors." (PMID 35205666, 2022). "In summary, we demonstrate that the developmental transcription factor, SOX9, confers cellular plasticity and promotes EMT in pancreatic cancer cells." (PMID 35205666, 2022). "For this, we silenced SOX9 in Panc-1 and RWP-1, two highly invasive and metastatic human pancreatic cancer cell lines, both with elevated endogenous levels of SOX9." (PMID 35205666, 2022). "Consistent with this, the levels of SOX9 were higher in metastatic cell lines such as IMIMPC-1, RWP-1, Hs766T, and the highly pro-metastatic cell line Panc-1, than in the primary pancreatic cancer cell lines." (PMID 35205666, 2022). "To identify the correlation between the expression levels of TSPAN8, SOX9 and EGFR in PDAC, we performed IHC analysis of an additional cohort of 40 human pancreatic cancer specimens." (PMID 34163029, 2021). "Accordingly, ectopic BMI1 also abrogated significantly the induction of apoptosis promoted by SOX9 silencing, reducing by over 50% the percentage of cells with active Caspase-3 and proteolyzed PARP1 in gastric and pancreatic cancer cells." (PMID 31941916, 2020). "SOX9 has been found expressed in the pancreatic CSCs isolated from PANC1 and HPAC cell lines of pancreatic cancer." (PMID 31057614, 2019).
pancreatic cancer (continued). "The PANCALYZE trail aims to predict the clinical course of pancreatic cancer on the basis of CXCR4, SMAD4, SOX9 and IFIT3 expression." (PMID 28356064, 2017). "The down-regulation of the SOX9 expression did not result in the anticipated enhancement of the epithelial status of the pancreatic cancer cell lines." (PMID 40141294, 2025). "Our discovery that miR-485-3p targets SOX9 and SLC7A11 to inhibit stemness-like properties and gemcitabine resistance provides new insights into the regulation of hypoxia, CSCs, and chemoresistance in pancreatic cancer." (PMID 38811540, 2024). "It was rather unexpected that the downregulation of SOX9 in all the six investigated pancreatic cancer cell lines did not significantly alter the expression of cyclin D1 (CCND1) and PCNA." (PMID 35884771, 2022). "The biological significance of deregulated SOX9 expression in the pathologic transformation of cellular processes and signaling pathways in pancreatic cancer cells has not been extensively studied yet." (PMID 35884771, 2022). "The role of SOX9 in the formation and maintenance of various pancreatic tumor cell phenotypes has not been thoroughly studied." (PMID 35884771, 2022). "The level of expression of another EMT-related transcription factor, ZEB1, did not change in pancreatic cancer cell lines after the downregulation of SOX9." (PMID 35884771, 2022). "We performed scratch assays with live-cell microscopy in pancreatic cancer cells with and without SOX9 silencing." (PMID 35205666, 2022). "MYEOV promotes pancreatic cancer progression by increasing HES1 expression and SOX9 transactivity." (PMID 35077391, 2022). "Importantly, SOX9 expression was elevated in gemcitabine resistant cells to a level only reached by CD133, one of the best-established stem cell markers in pancreatic cancer." (PMID 35205666, 2022). "The downregulation of SOX9 did not lead to detectable changes in the expression of the transcription factor FOXA1 in all the six investigated pancreatic cancer cell lines." (PMID 35884771, 2022). "Moreover, increased SOX9 and TSPAN8 levels were shown to correlate in human pancreatic cancer specimens and downregulated in vitro by EGFR tyrosine kinase inhibitors." (PMID 34163029, 2021). "In pancreatic cancer, there is evidence that PDAC and APC have high expression of Sox9." (PMID 31057614, 2019). "Thus, the downregulation of the SOX9 expression did not lead to the expected enhancement of the epithelial status of the cells of the pancreatic cancer lines studied." (PMID 35884771, 2022). "Another type of pancreatic cancer called intraductal papillary mucinous neoplasm (IPMN) is less aggressive than PDAC and APC and exhibits a characteristic expression of SOX9 confined to the lower portions of IPMN which is lost once the neoplasms advance to high-grade dysplasia carcinoma." (PMID 31057614, 2019). "Surprisingly, SOX9 overexpression did not alter the expression of SNAIL or other well-known EMT transcription factors such as SLUG or ZEB1 in BxPC-3 and IMIMPC-2 pancreatic cancer cells; however, the expression of the BMI1 stem cell factor was elevated." (PMID 35205666, 2022). "The acquired data do not allow us to verify the role of SOX9 as the regulator of EMT and the activator of mesenchymal differentiation genes in pancreatic tumors." (PMID 35884771, 2022).
osteosarcoma (39 papers, 2011 to 2025). A usually aggressive malignant bone-forming mesenchymal neoplasm, predominantly affecting adolescents and young adults. "In tumors, SOX9 was described to be implicated in chordoma and osteosarcoma, where its overexpression promotes invasion and proliferation, supporting a role in endothelial-mesenchymal transition." (PMID 41303462, 2025). "Although Sox9 is related to the prognosis and severity of osteosarcoma, it cannot provide an auxiliary diagnostic role in the pathological differentiation of osteosarcoma and chondrosarcoma." (PMID 38978960, 2024). "In the study of osteosarcoma, it was found that miR-590-3p, miR-1225-5p, miR-320a, and miR-30c can directly interact with specific binding to Sox9, causing Sox9 degradation or inhibiting its expression." (PMID 38978960, 2024). "As a potential therapeutic and diagnostic target for osteosarcoma stem cells, Sox9 requires more clinical research data." (PMID 38978960, 2024). "More recently, Sox9 has been implicated in the development and progression of several types of cancer, including osteosarcoma." (PMID 38978960, 2024). "The molecular mechanism involves the degradation of SRY-box-9 (SOX9), associated with increased aggressiveness in osteosarcoma." (PMID 38534381, 2024). "Then, immunohistochemistry was performed to analyze the association of SOX9 expression in 166 osteosarcoma tissues with clinicopathological factors or survival of patients." (PMID 24188461, 2013). "The major finding of our study is that the upregulation of SOX9 expression is associated with the progression of osteosarcoma." (PMID 24188461, 2013). "Then, we analyzed the associations of SOX9 expression with various clinicopathological parameters of osteosarcoma tissues." (PMID 24188461, 2013). "Furthermore, immunofluorescent colabeling of SOX9 and vimentin—two hallmark markers of osteosarcoma—confirmed that the PDOs preserved key molecular characteristics of their parental tumors." (PMID 41382267, 2025). "Likewise, SOX9 expression was shown to drive mesenchymal proliferation and extracellular matrix remodeling in chordoma and osteosarcoma models, while GATA4 has recently been linked to myogenic reprogramming and mesodermal lineage persistence." (PMID 41303462, 2025). "In addition to its role in osteosarcoma, Sox9 has also been implicated in the development of several other types of cancer, including liver cancer, prostate cancer, and lung cancer." (PMID 38978960, 2024). "Understanding the role of Sox9 in osteosarcoma may lead to a better understanding of the underlying mechanisms of this type of cancer." (PMID 38978960, 2024). "Sox9 is involved in the effector mechanism of osteosarcoma growth caused by hypoxia." (PMID 38978960, 2024). "Sox9, a transcription factor known for its critical role in embryonic development and tissue homeostasis, has been implicated in various malignancies, including osteosarcoma." (PMID 38978960, 2024). "Downregulated SOX9 has been reported in osteoarthritic articular cartilage, while osteosarcoma and chondrosarcoma exhibit upregulation of SOX9 together with proliferative chondrocytes." (PMID 40025280, 2025). "Additional predicted targets of miR-30a and miR-30e within this pathway include PIK3CA, mTOR, FOXO3, MMP13, SOX9, BCL2, VEGFA, and CCND1, all of which have been previously associated with osteosarcoma pathogenesis." (PMID 40862758, 2025). "Osteosarcoma cells express Runx2 and Sox9 genes, showing features of osteoblastic and chondrogenic differentiation." (PMID 39896817, 2024). "Integration of emerging technologies such as single-cell RNA sequencing and functional genomics will provide deeper insights into the heterogeneity and plasticity of osteosarcoma CSCs and their regulation by Sox9." (PMID 38978960, 2024). "Targeting Sox9 in osteosarcoma CSCs holds promise for developing novel treatment strategies aimed at eradicating the CSC population, reducing tumor heterogeneity, and improving patient outcomes." (PMID 38978960, 2024).
osteosarcoma (continued). "Inhibition of Sox9 using siRNA has been shown to reduce the expression levels of Wnt1 and Fzd1, resulting in a significant reduction of osteosarcoma cell proliferation." (PMID 38978960, 2024). "If SUMOylated, SOX9 cannot be ubiquitinated and degraded, making the activity of SENP2 necessary for SOX9 degradation and the consequent reduced osteosarcoma cell proliferation, thus characterizing this SENP as a tumor suppressor." (PMID 38534381, 2024). "This review aims to summarize the current knowledge regarding the role of Sox9 in CSCs in osteosarcoma and its potential implications as a prognosis and therapeutic target." (PMID 38978960, 2024). "We believe that designing anti-tumor drug delivery systems targeting Sox9 is very promising for the treatment of osteosarcoma." (PMID 38978960, 2024). "Studies have shown that Sox9 is over-expressed in cases of dog osteosarcoma, suggesting that it plays a role in the development and progression of this disease." (PMID 38978960, 2024). "KDM3A binds to the gene promoter region of Sox9 and promotes the expression of Sox9, thereby promoting the proliferation and migration of osteosarcoma." (PMID 38978960, 2024). "Several studies have reported the correlation between Sox9 expression and the clinical outcome of osteosarcoma patients." (PMID 38978960, 2024). "Osteosarcoma and chondrosarcoma cells express Runx2 and Sox9 genes, indicating osteogenic and chondrogenic differentiation, respectively." (PMID 39896817, 2024). "Abnormal expression of SOX9 is involved in various cancers, such as osteosarcoma, lung cancer, and breast cancer." (PMID 38280996, 2024). "Overall, understanding the role of Sox9 in osteosarcoma CSCs has significant implications for prognosis prediction, targeted therapy development, and personalized treatment approaches." (PMID 38978960, 2024). "The study identifies Sox9 as the key transcription factor mediating the effects of melatonin, with melatonin inhibiting CSCs by downregulating the Sox9-mediated signaling pathway in osteosarcoma." (PMID 38978960, 2024). "In conclusion, the emerging evidence suggests that Sox9 plays a significant role in the regulation of CSCs in osteosarcoma." (PMID 38978960, 2024). "To evaluate the effect of SOX9 knockdown on the survival of osteosarcoma cells in vitro, we employed cleaved caspase-3 immunoblotting and propidium iodide staining techniques." (PMID 37491298, 2023). "Our focus on SOX9 is based on our previous study, which demonstrated that SOX9 promotes the development of chondroblastic osteosarcoma from mesenchymal stem/stromal cells." (PMID 37491298, 2023). "Reference 1 Wu H, He Y, Chen H, Liu Y, Wei B, Chen G, Lin H and Lin H LncRNA THOR increases osteosarcoma cell stemness and migration by enhancing SOX9 mRNA stability." (PMID 37219054, 2023). "THOR promoted osteosarcoma CSC stemness via increasing SOX9 mRNA stability and upregulating its expression." (PMID 35252166, 2022). "From osteoblasts to osteosarcoma, SOX9, SPP1 (osteopontin) and RUNX2 were also considered as origin-related factors." (PMID 34828292, 2021). "For example, low expression of miR-1225-5p is correlated with poor prognosis in patients with osteosarcoma, and its overexpression inhibits osteosarcoma cell invasion and metastasis by targeting Sox9." (PMID 35154253, 2021). "Another in vitro study shows that melatonin potently suppresses migration and invasion in human osteosarcoma HOS and U2OS cells, and inhibits the sarcosphere formation of osteosarcoma stem cells via the down-regulation of SOX9-mediated signaling pathway." (PMID 31842295, 2019). "Two other studies showed that miR-32 suppresses osteosarcoma cell proliferation and invasion through regulating Sox9 expression and promotes CRC cells proliferation, migration, and invasion and reduces apoptosis by targeting PTEN." (PMID 28149200, 2017).